FARP1 (FERM, ARH/RhoGEF and pleckstrin domain protein 1)
Description:
Functions as a guanine nucleotide exchange factor for RAC1. May play a role in semaphorin signaling. Plays a role in the assembly and disassembly of dendritic filopodia, the formation of dendritic spines, regulation of dendrite length and ultimately the formation of synapses (By similarity).
Synonyms: CDEP; PLEKHC2; MGC87400; PPP1R75; GLCC1; FARP1-IT1
Tractability: Antibody: UniProt places it where antibodies can reach, with medium confidence; its Gene Ontology location is reachable by antibodies, with medium confidence. PROTAC: ubiquitination databases record sites on it; its protein half-life has been measured.
Gene: Protein-coding gene on chromosome 13 (98,142,165 to 98,455,176, forward strand). Ensembl gene ENSG00000152767.
Subcellular location: Cell membrane; Synapse; Synapse, synaptosome; Cytoplasm, cytosol; Cell projection, filopodium; Cell projection, dendrite; Cell projection, dendritic spine
Subcellular location (Human Protein Atlas): Cytosol
Pathways (Reactome):
Signal Transduction: CDC42 GTPase cycle; RAC1 GTPase cycle; RHOA GTPase cycle; RHOF GTPase cycle
Gene Ontology:
Molecular function: protein binding; guanyl-nucleotide exchange factor activity; cytoskeletal protein binding; small GTPase binding
Biological process: dendrite morphogenesis; synapse assembly; enzyme-linked receptor protein signaling pathway; postsynaptic actin cytoskeleton organization; Rac protein signal transduction; regulation of presynapse assembly; retrograde trans-synaptic signaling by trans-synaptic protein complex
Cellular component: cytoplasmic side of plasma membrane; cytoskeleton; cytosol; dendrite; dendritic spine; extrinsic component of postsynaptic membrane; filopodium; glutamatergic synapse; plasma membrane; synapse
Genetic constraint (gnomAD): Loss-of-function variants: 42 observed, 99.19 expected, observed/expected ratio (o/e) 0.42, 90% interval 0.33 to 0.55. The upper end of that interval is the gene's LOEUF score, 0.55, which puts it in group 2 of 6, group 1 being the genes least tolerant of losing a copy. Missense variants: 1,179 observed, 1,222.3 expected, observed/expected ratio (o/e) 0.96, 90% interval 0.92 to 1.01. Synonymous variants: 509 observed, 507.55 expected, observed/expected ratio (o/e) 1, 90% interval 0.93 to 1.08.
Homologues: Orthologues: chimpanzee FARP1 (99% identical), macaque FARP1 (98% identical), guinea pig FARP1 (93% identical), rabbit FARP1 (93% identical), rat Farp1 (92% identical), mouse Farp1 (92% identical), dog FARP1 (92% identical), pig FARP1 (91% identical), tropical clawed frog FARP1 (75% identical), zebrafish farp1 (69% identical), Caenorhabditis elegans frm-3 (28% identical), Caenorhabditis elegans exc-5 (14% identical). Paralogues in human: FARP2 (55% identical), FRMD7 (26% identical), FGD6 (19% identical), FGD5 (18% identical), FGD1 (16% identical), FGD4 (16% identical), FGD2 (13% identical), FGD3 (13% identical), ECT2L (10% identical), ARHGEF39 (7% identical).
Diseases named in the same sentence as FARP1 in open-access papers:
FARP1 is named in the same sentence as 23 diseases in open-access papers, as found by Europe PMC text mining. Sharing a sentence is not in itself a finding about the gene and the disease. The quoted sentences say what the papers report.
gastric cancer (5 papers, 2020 to 2025). A primary or metastatic malignant neoplasm involving the stomach. "Pathophysiologically, increased FARP1 levels are linked to reduced patient survival in cutaneous melanoma and gastric cancer." (PMID 41299419, 2025). "In this study, we showed that FARP1 overexpression was significantly associated with lymphatic invasion, lymph metastasis, and poor prognosis in patients with advanced gastric cancer, and that it promoted gastric cancer cell motility by activating CDC42." (PMID 32029704, 2020). "FARP1 (pleckstrin domain protein 1) expression is related to poor prognosis of advanced gastric cancers." (PMID 37771441, 2023). "Overexpression of FARP1 was significantly correlated with lymph metastasis, lymphatic invasion and poor prognosis in advanced gastric cancer patients." (PMID 34252883, 2021). "In the present study, we examined correlation between FARP1 expression and the prognosis of patients with gastric cancer, and explored the potential role of the integrin αvβ5-FARP1-CDC42 axis in promoting cancer cell migration and invasion." (PMID 32029704, 2020). "This is consistent with the observation that the overexpression of FARP1 protein correlates with unfavorable prognosis in patients with advanced gastric cancer." (PMID 32029704, 2020). "FARP1 interacted with integrin β5, and a potent integrin αvβ5 inhibitor (SB273005) prevented cell motility in only high FARP1-expressing gastric cancer cells." (PMID 32029704, 2020). "In gastric cancer cells, FARP1 knockdown decreased cell motility, whereas FARP1 overexpression promoted cell motility and filopodium formation via CDC42 activation." (PMID 32029704, 2020). "FARP1 promoted cell motility through activating CDC42 in gastric cancer." (PMID 34252883, 2021). "To investigate whether the expression of FARP1 plays a role in gastric cancer development, we performed immunohistochemical analysis of 91 advanced gastric cancer samples." (PMID 32029704, 2020). "In addition, we found that inhibition of the integrin αvβ5 receptor significantly decreased the cell motility capability in high FARP1-expressing gastric cancer cells." (PMID 32029704, 2020). "Our in silico analysis indicated that high mRNA expression levels of integrin β5 were correlated with a poor prognosis of patients with gastric cancer; moreover, we provided the first demonstration of the interaction between FARP1 and integrin αvβ5 in gastric cancer cell lines." (PMID 32029704, 2020). "Lastly, blocking FARP1 could be a promising gastric cancer treatment." (PMID 39409942, 2024). "Therefore, the suppression of an autoinhibitory mechanism through the conformational change effected by interacting with integrin αvβ5 and phosphorylation by EGFR-MAP4K4 signaling might, in turn, regulate FARP1 activity in gastric cancer cells." (PMID 32029704, 2020). "We conducted in silico analyses of The Cancer Genome Atlas expression data to identify candidate Rho-GEF genes showing aberrant expression in advanced gastric cancer and found FERM, Rho/ArhGEF, and pleckstrin domain protein 1 (FARP1) expression is related to poor prognosis." (PMID 32029704, 2020). "Thus, it appears reasonable to conclude that FARP1 activates CDC42 and facilitates the abilities of cell migration and invasion by promoting the formation of filopodia and invadopodia in gastric cancer." (PMID 32029704, 2020). "Therefore, FARP1 and TRIO may involve in gastric cancer cell migration, invasion and poor prognosis in a synergistic manner." (PMID 32029704, 2020).
cholangiocarcinoma (1 paper, 2025). A carcinoma that arises from the intrahepatic biliary tree (intrahepatic cholangiocarcinoma) or from the junction, or adjacent to the junction, of the right and left hepatic ducts (hilar cholangiocarcinoma). "These include FARP1 (found in 2 RASGRF2 fusions from cholangiocarcinoma and PDAC) and MSH3 (found in 6 RASGRF2 fusions from colorectal, ovarian, head and neck, pancreatic, and prostate cancers)." (PMID 40615519, 2025).
lung carcinoma (1 paper, 2022). "For instance, it was recently reported that the A549 lung cancer cell line was dependent on the GEFs ARHGEF39, FARP-1, and TIAM-2 while the MDA-MB-231 and GFP-HER2-BM cells have a different GEF compliment and express Vav." (PMID 36861094, 2022).
Lymphatic Metastasis (1 paper, 2020). Transfer of a neoplasm from its primary site to lymph nodes or to distant parts of the body by way of the lymphatic system. "The expression of FARP1 protein was associated with lymphatic metastasis (N) (P = 0.012), lymphatic invasion (ly) (P = 0.025) and recurrence rate (P = 0.002) but not with age, sex, pathological type, depth of invasion (T), pathological stage (pStage), venous invasion (v), or recurrence pattern." (PMID 32029704, 2020).
neuroblastoma (1 paper, 2024). Neuroblastoma (NB) is the most common solid, extracranial childhood tumor. "In SH-SY5Y neuroblastoma models, we show that ANKK1 interacts with the synapse protein FERM ARH/RhoGEF and Pleckstrin Domain 1 (FARP1), which is a guanine nucleotide exchange factor (GEF) of the RhoGTPases RAC1 and RhoA." (PMID 39409035, 2024). "In the neuroblastoma cells SH-SY5Y, co-IP of endogenous ANKK1 and FARP1 demonstrated their interaction under proliferative (neuroblast-like) or serum-starved conditions (0% fetal bovine serum, FBS) that induce neural differentiation (neuronal-like)." (PMID 39409035, 2024).
pancreatic cancer (1 paper, 2022). "This included elements of the Hedgehog signaling pathway (SHH, GAS1), semaphorin signaling (SEMA3A, PLXNA1, PLXNB2, PLXND1, PLXNA2, FARP1, FARP2) and also axon guidance pathways (ROBO1, SLIT1, SLIT3 and SLITRK2), all notable for their involvement in pancreatic cancer progression and metastasis." (PMID 36429078, 2022).
tumor (9 papers, 2019 to 2025). "Genomic DNA sequencing revealed 2 pairs of bilateral tumors harboring the same BRAF V600E mutation, while the remaining pair of bilateral PTC had different genetic mutations, with BRAF V600E mutation in the right tumor and RET/FARP1 fusion in the left tumor." (PMID 35515000, 2022).
cancer (8 papers, 2019 to 2024). A tumor composed of atypical neoplastic, often pleomorphic cells that invade other tissues. "Further, FARP1 levels in patients are linked to cancer spreading." (PMID 39409942, 2024). "Cancer-associated fibroblast-specific circ-FARP1 binds to CAV1 and inhibits its ubiquitination by ZNRF1 to enhance the secretion of LIF; in addition, circ-FARP1 sponges miR-660-3p to increase the expression of LIF, thereby promoting the stemness and GEM resistance of PDAC cells." (PMID 38044421, 2023). "In this way, FARP1 promotes cancer cell spread by interacting with the integrin β5 and activating another protein called CDC42." (PMID 39409942, 2024). "The roles of FARP1 expression in cancer development are not well understood." (PMID 32029704, 2020). "However, the impact of FARP1 expression in cancer remains poorly understood." (PMID 32029704, 2020). "The Cancer Genome Atlas (TCGA) data analysis indicated that the gene expression of TRIO, NET1, ECT2, TIAM2, FARP1, ARHGEF12 and BCR in primary cancer was significantly higher than those in normal tissues." (PMID 32029704, 2020). "We further focused on FARP1, which has never been reported to have clinical significance in cancers." (PMID 32029704, 2020).
infection (2 papers, 2020 to 2023). The state of being infected such as from the introduction of a foreign agent such as serum, vaccine, antigenic substance or organism. "The increase in Bgl-FaRP1 expression observed here agrees with previous studies that measured neuropeptide responses to infection in gastropods." (PMID 37352363, 2023). "This increase appears to occur primarily in Egp cells with low Bgl-FaRP1 expression levels prior to infection." (PMID 37352363, 2023). "Together, these observations indicate that expression of the Bgl-FaRP1 tetrapeptide (FMRF-NH2) precursor is increased in specific cell clusters relatively late in the infection chronology." (PMID 37352363, 2023). "Unlike the heptapeptide precursor, expression of the Bgl-FaRP1 tetrapeptide precursor was affected by infection by S. mansoni." (PMID 37352363, 2023).
infectious disease (1 paper, 2019). A disorder directly resulting from the presence and activity of a microbial, viral, or parasitic agent in humans. "The second is between pspC−9 and position 98891272 on chromosome 13 (MAF = 0.16; OR = 6.30; p = 3.6 × 10–8) in FARP1, a gene not previously associated with infectious disease but expressed in the brain." (PMID 31092817, 2019).
FARP1 also shares sentences with these, for which no sentence is quoted: colorectal cancer (10 papers); colon cancer (2); cutaneous melanoma (2); autism (1); breast carcinoma (1); cardiovascular disease (1); colorectal (1); hepatocellular carcinoma (1); lung adenocarcinoma (1); non-small cell lung carcinoma (1); osteosarcoma (1); prostate carcinoma (1); rectal cancer (1).